STAT3 (signal transducer and activator of transcription 3)
Diseases named in the same sentence as STAT3 in open-access papers (continued):
Sharing a sentence is not in itself a finding about the gene and the disease.
tumor (continued). "Indeed, inhibiting STAT3 in tumor cells, or its activators in macrophages, causes a significant decrease in MMP expression and migration in tumor cells." (PMID 39555068, 2024). "This illustrates the importance of STAT3 in the regulation of tumor evasion of the immune system." (PMID 38464736, 2024). "Moreover, AnxA1, known to regulate the nuclear localization of EGFR, promotes T cell dysfunction by favoring the EGFR/STAT3 transcriptional activities in cancer cells, enhancing immune evasion and tumor progression." (PMID 38645221, 2024). "Blocking IL-6-stimulated STAT3 activation in these cells may lead to alterations in cytokines within the tumor microenvironment." (PMID 38426090, 2024). "Mechanistically, RNF122 may enhance tumor progression through JAK2/STAT3/c‐Myc signaling pathway activation." (PMID 39218810, 2024). "All this evidence suggests that the activation of STAT3 can promote glycolysis in tumor cells." (PMID 39816354, 2024). "In our previous research 9, we demonstrated that M2-like tumor-associated macrophages (TAMs) secrete TGFBI, promoting GBM growth through integrin αvβ5-Src-Stat3 signaling, emphasizing the significance of TGFBI in the immune microenvironment of GSCs under normoxic conditions." (PMID 39346536, 2024). "Toxoplasma gondii (T.gondii) Rhoptry protein 16 (ROP16) has been shown to quickly enter the nucleus, and through activate host cell signaling pathways by phosphorylation STAT3 and may affect the survival of tumor cells." (PMID 39174877, 2024). "Indeed, numerous studies have revealed the role of NF-κB and STAT3 signaling in promoting tumor-cell proliferation, survival, migration, invasion, autophagy, angiogenesis and metastasis in various cancers." (PMID 38926796, 2024). "Intriguingly, STAT3 has been shown to mediate the acetylation of NF-κB, enhancing its nuclear retention through the recruitment of acetyltransferase p300.STAT3-mediate acetylation activity leads to continuous NF-κB, which is crucial for alter of tumor microenvironment." (PMID 39493763, 2024). "The activation of Stat3 signaling in tumor-adjacent cells, may propose a rapid response of brain microenvironmental cells to brain colonizing tumor cells." (PMID 38386085, 2024). "The genomic profile of the tumor may further elucidate if STAT3 performs in an oncogenic or tumor suppressive fashion in each tumor." (PMID 38339245, 2024). "Additionally, IL-23 further activates STAT3, RORα, and RORγt in Th17 cells, maintaining their chronic inflammatory environment, thereby promoting tumor formation." (PMID 38755133, 2024). "Stationary markers, such as the protein expression of Signal Transducers and Activators of Transcription 3 (STAT3) and Cyclin D1, or whole cell populations within the tumor, particularly tumor-infiltrating leukocytes, were reported to be associated with survival outcomes." (PMID 38392590, 2024). "STAT3 activation promotes angiogenesis, tumor invasion, metastasis, and cell cycle progression." (PMID 39524444, 2024). "Interestingly, STAT3 activation in tumor cells can significantly impair NK cell antitumor immunity via multiple mechanisms." (PMID 38596684, 2024). "STAT3 and MAPK can also be linked to arginase action and modulate tumor growth and progression." (PMID 39337272, 2024). "Increased STAT3 activity in a tumor likewise protects a tumor from immune-based destruction." (PMID 38611065, 2024). "Therefore, STAT3 regulated by circRNA is involved in tumor cell proliferation, metastasis, apoptosis, and chemoresistance." (PMID 39584047, 2024). "The activation of STAT3 subsequently induces tumor cell proliferation." (PMID 38317142, 2024). "Thus, constitutive activation of STAT3 in cancer cells promotes cell survival and proliferation and inhibits apoptosis, which benefits tumor growth." (PMID 38256080, 2024).
tumor (continued). "However, some tumors secrete immunosuppressive cytokines like interleukin-10 (IL-10), which activate STAT3 in immune cells, leading to the suppression of antitumor responses and promoting tumor immune evasion." (PMID 39483536, 2024). "Furthermore, the localization of radioactivity was almost consistent with STAT3 expression based on ex vivo autoradiography and immunohistochemistry using adjacent tumor sections." (PMID 38834900, 2024). "Indeed, IL-22, after binding IL-22R, leads to STAT3 pathway activation and is related to the progression of different neoplasms, including pancreatic, colon, breast, and lung cancers." (PMID 38607023, 2024). "STAT3 was found to be strongly expressed in the tumor tissue of TNBC mice in this study, and ginsenoside Rh2 could inhibit its expression." (PMID 39845783, 2024). "Additionally, it reveals that the target gene of C6 ceramide, EGR3, can effectively exert anti-tumor effects by regulating the JAK1/STAT3 signaling pathway." (PMID 38338065, 2024). "Finally, it was reported that STAT3 knockdown promoted sorafenib-induced ER stress-induced apoptosis in HCC cells enhancing the anti-tumor function of CD8+ T and NK cells." (PMID 38891056, 2024). "Targeting the STAT3 pathway in cancer cells may govern the growth of gastric tumors and impact immune cell polarization toward an anti-tumor Th17 population." (PMID 39676857, 2024). "Moreover, M2-polarized macrophages convert to the anti-tumor M1 type when STAT3 signaling is disrupted." (PMID 38245798, 2024). "Mechanistically, we revealed that SERPINA1 might mediate CEBPB-induced promotion of tumor cell growth and migration via STAT3 signaling for the first time." (PMID 38710698, 2024). "However, sustained activation of JAK2/STAT3 signaling had been found in many solid tumors, such as breast cancer, which promoted solid tumorigenesis, tumor growth, angiogenesis, host immune evasion, apoptosis resistance, carcinogenesis, and metastasis." (PMID 38420199, 2024). "Indeed, we have previously shown that conditional genetic ablation or therapeutic inhibition of Stat3 in tumor-bearing Gp130FF mice reduces their tumor burden in the stomach." (PMID 37957015, 2024). "As shown in screened eleven oxidative stress-related DEGs, AKR1B1 is necessary for tumor growth and was found to interact with signal transducer and activator of transcription 3 (STAT3), participating in anti-cell death processes and leading to drug resistance." (PMID 39351147, 2024). "Additionally, research has shown that elevated ROS levels can inhibit tumor growth by suppressing JAK2/STAT3 signaling in different cancers." (PMID 38402166, 2024). "STAT3, often overactivated in human cancers, including GI tumors, stimulates the transcription of genes involved in metastasis, anti-apoptosis, proliferation, and survival, thus accelerating tumor growth, metastasis, and drug resistance." (PMID 39767561, 2024). "Radioactivity peaked later in the tumor than in blood and muscle, which are representative nontarget tissues, suggesting active targeting of [18F]FBNAF to the tumor depending on the binding interaction with STAT3 in the xenograft mouse model used in this study." (PMID 38834900, 2024). "The effect of conjugated TNT with quercetin (TNT–Qu) on the B16F10 animal melanoma model proved that topical TNT–Qu could be applied to reduce tumor growth via regulating phospho‐STAT3 levels in the tumor." (PMID 38491817, 2024). "We next evaluated whether blocking CAF-CM-induced STAT3 phosphorylation affected GM-CSF gene expression in tumor cells." (PMID 39199680, 2024). "This interaction between STAT3 signaling and tumor-stroma has been noted in previous literature." (PMID 38424636, 2024). "Indeed, in metastasis models the STAT3 signaling pathway has been shown to mediate LRG1-driven tumor metastasis, and that this can be significantly reduced in Lrg1 deficient mice or following LRG1 antibody blockade." (PMID 38745756, 2024).
tumor (continued). "Moreover, Snail was confirmed to be one of the downstream molecules of JAK2/STAT3 in promoting tumor metastasis." (PMID 38182570, 2024). "Notably, these pathways often regulate tumor dynamics via downstream STAT3 signaling, underscoring the importance of exploring STAT3’s role in tumor pathology as a promising research direction." (PMID 39080273, 2024). "Thus, inhibition of the STAT3-ferroptosis inhibitory axis reduced tumor growth and alleviated chemoresistance." (PMID 38341410, 2024). "The constant activation of STAT3 has been documented across various tumour types, facilitated by mechanisms such as the hyperactivation of receptors for pro‐oncogenic cytokines and growth factors, the loss of negative regulation, and heightened cytokine stimulation." (PMID 39121240, 2024). "Through the STAT3 pathway, ferroptosis in tumor cells can promote fatty acid oxidation in macrophages, leading to their polarization towards the M2 subtype, which promotes tumor growth." (PMID 38853203, 2024). "In addition to activation in tumor cells, STAT3 signaling is essential for the differentiation of Th17 cells, inhibition of dendritic cell maturation, and maintenance of the immunosuppressive function of Foxp3+ Treg cells." (PMID 38892375, 2024). "Interestingly, research suggests that ACADL functions as a tumor suppressor in HCC by inhibiting metastasis via the signal transducer and activator of transcription 3 (STAT3)/Matrix Metalloproteinase 14 (MMP14) pathway." (PMID 38833109, 2024). "However, in CRC patients, tumor‐related NK cells have been found to secrete angiogenic factors through the STAT3 and STAT5 pathways to stimulate tumor blood vessel formation and invasion." (PMID 37903487, 2024). "Reports show that selective targeting of STAT3 in cancer could provide multiple benefits, including inhibiting cell-autonomous effects on tumor cell growth and metastasis." (PMID 39136000, 2024). "Scavenging ROS could restore tumor stemness, attenuate the inhibitory effect on the phosphorylation of STAT3, and promote cell proliferation." (PMID 38947380, 2024). "Moreover, the authors concluded that the tumor progression is due to the influence of NEAT1 on the miR-26a/b-5p/STAT3 axis by sponging the miRNA, which increases YKL-40 expression." (PMID 39188680, 2024). "Tumor radioactivity was significantly reduced by the coinjection of a STAT3-selective inhibitor." (PMID 38834900, 2024). "Similarly, replacement therapy with tumor suppressor miR-34a can downregulate IL6 expression and suppress the pro-inflammatory effects associated with IL6/STAT3 activation, thereby aiding tumor suppression and invasion control in OC." (PMID 39766086, 2024). "Additionally, OASL regulates immune checkpoint ligand such as programmed death ligand 1 (PD-L1), through IFN-γ/STAT1 and IL-6/JAK/STAT3 pathways in tumor cells." (PMID 39286258, 2024). "Expression of activated forms of mTOR and STAT3 significantly reduced tumor cell killing." (PMID 38758815, 2024). "Consequently, combination STAT3 inhibition with immune checkpoint inhibitor is a promising strategy to improve the clinical response in tumor patients." (PMID 38245798, 2024). "In NSCLC, activation of the JAK1/STAT3 pathway is considered to be crucial for tumor progression." (PMID 39209829, 2024). "Additionally, STAT3 has been implicated in elevated tumor malignancy and PD-L1 expression through VEGF in tumor cells." (PMID 38822331, 2024). "The expression of circKIF4A in brain metastasis from TNBC was significantly increased, and it could promote the expression of STAT3 and p62 through competitive adsorption of miR‐637, which induced tumor autophagy and metastasis." (PMID 39584047, 2024). "However, B cells also provide pro-tumoral effects by activating STAT3, enabling pathological angiogenesis and facilitating tumor progression." (PMID 39769501, 2024).
tumor (continued). "In conclusion, we explored the crucial role of HLJ1 in alleviating DEN-induced carcinogenesis through multiple mechanisms: DNA damage attenuation, inhibition of compensatory proliferation, and down-regulation of phosphorylated STAT3 in normal liver tissue, ultimately reducing tumor burden." (PMID 39738726, 2024). "In addition to being an oncogene and transcription activator, STAT3 is essential for tumor cell proliferation, invasion, and migration." (PMID 38397437, 2024). "STAT3 serves as a key signaling node for tumor cells, especially tumor infiltrating immune cells." (PMID 38172648, 2024). "Additionally, the potential for leveraging the upregulation of CXCL12 and the subsequent activation of the STAT3 pathway to prevent tumor metastasis warrants further investigation." (PMID 38920657, 2024). "Targeting STAT3 in cancer cell lines and in-vivo studies has also reduced tumor growth." (PMID 38571491, 2024). "Tumour cell-derived granulocyte macrophage-colony stimulating factor (GM-CSF) activates MDSCs via inducing STAT3-mediated fatty acid transport protein 2 (FATP2), and pharmacological blockade of the latter via lipofermata reduced ROS expression, MDSC immunosuppressive activity, and tumour burden." (PMID 38464388, 2024). "CD276 promotes epithelial-mesenchymal transition (EMT) and HCC invasion through the JAK2/STAT3/slug pathway and induces M2 polarization of tumor-associated macrophages (TAMs) to promote an immunosuppressive tumor microenvironment (TME) in a STAT3-dependent manner." (PMID 39640777, 2024). "In our study, we found 1G11 blocked the LIF/LIFR/STAT3 axis in tumor cells in vitro." (PMID 39169307, 2024). "Shift to the complexity of the tumor microenvironment: Research has begun to emphasize the role of macrophages as key components of the tumor microenvironment, particularly focusing on blocking the STAT3/IL-10 pathway related to IL-10, which has seen extensive study in recent years." (PMID 39034998, 2024). "Hence, we will further explorethe impact of YY002 on the tumor microenvironment, and also investigatethe distinctive role of STAT3 Tyr705 or Ser727 phosphorylation inmodulating the tumor microenvironment." (PMID 38559310, 2024). "We examined whether the accumulation of radioactivity in the tumor was attributable to the interaction of [18F]FBNAF with STAT3 using a blocking study with the STAT3-selective inhibitor BP-1–102." (PMID 38834900, 2024). "This is of importance, as the previous animal studies that described tumor-stroma IL-6/STAT3 communication and reported the efficacy of the combined STAT3 and MEK inhibition to overcome immunotherapy resistance in PDAC did not report the sex of the animals used." (PMID 39684385, 2024). "To determine whether KRAS-dependent tumor cells are co-dependent on STAT3, we used two wellestablished models of KRAS mutant cancer: mouse embryonic fibroblasts and pancreatic ductal adenocarcinoma (PDAC) cells expressing endogenous KRASG12D." (PMID 38573819, 2024). "The ability of IL‐6 to initiate ferroptosis is equally striking, which can disrupt intracellular iron homeostasis via JAK/STAT3 while using protein kinase (ERK) as a signalling amplifier inhibition of the antioxidant function of the xc‐system catalyses ferroptosis in tumour cells." (PMID 38652105, 2024). "There are some neoplasms resistant to drug therapies due to STAT3 overactivity, and in those cases, STAT3-dependent alkaliptosis may be an appropriate treatment strategy." (PMID 39768186, 2024). "STX-0119, a STAT3 dimerization inhibitor, combined with nivolumab (anti-PD-1 antibody), shows more dramatic inhibitory effects on the tumor growth and tumor-infiltrating lymphocyte numbers than STX-0119 and nivolumab single treatment in PANC-1 pancreatic cancer cells xenograft." (PMID 38245798, 2024). "STAT3 and NF-kB promote the activation of anti-apoptotic genes in tumor cells." (PMID 38610706, 2024).
tumor (continued). "In addition, we employed qRT‐PCR to assess the RNF122, JAK2, and STAT3 expression levels in tumor samples and performed correlation analysis." (PMID 39218810, 2024). "In addition, several studies have shown that STAT3 is involved in the regulation of tumor radioresistance." (PMID 38605477, 2024). "Ultimately, celastrol prevented the formation of human HCC xenograft tumors in athymic nu/nu mice and reduced STAT3 activation in tumor tissues when administered intraperitoneally without causing any adverse effects." (PMID 38397437, 2024). "Aberrant STAT3 signaling exerts oncogenic effects by promoting tumor proliferation, survival, chemoresistance, invasion, metastasis, angiogenesis, immunosuppression, and tumor-related inflammation." (PMID 38596684, 2024). "We also investigated the effects of RSJ on the Jak2/Stat3 signaling pathway in tumor tissue." (PMID 39203920, 2024). "Here, we highlight the critical role of Redox effector 1 (Ref-1) in PDAC progression and drug resistance, focusing on its redox regulation of key transcription factors (TFs) such as STAT3, HIF1α, and NF-κB, which are pivotal for tumor survival, proliferation, and immune evasion." (PMID 39635662, 2024). "Notably, in vitro, xenograft model indicated that CAFs can facilitate tumor progression through the IL-10/JAK1/STAT3 signaling pathway." (PMID 39511039, 2024). "Its anticancer prowess was observed to disrupt the G1/S phase, inducing apoptotic pathways through caspase-3 activation, and orchestrating the downregulation of pivotal cellular regulators such as STAT3, P21, P27, IL-6, and AhR, thereby impeding tumor progression." (PMID 38653790, 2024). "In NPC, STAT3 plays a pivotal role in tumour progression, metastasis, and therapeutic resistance." (PMID 39121240, 2024). "And the inhibition of STAT3 expression significantly suppresses tumor growth and proliferation." (PMID 39845783, 2024). "However, G-CSF contributes to the proliferation and metastasis of tumor cells by activating STAT3, which directly acts on the corresponding target genes and microRNA genes that control cell differentiation and stemness." (PMID 39129784, 2024). "In addition, PARP inhibitors also enhance the signal transduction and activator of transcription (STAT3) pathway in tumor cells, promoting the pro-tumor polarization of TAM." (PMID 39318358, 2024). "Similarly, tumor-derived kynurenine hyperactivates Tregs, leading to increased IL-10 secretion which promotes chemotherapy resistance in gastric cancer via the STAT3/BCL2 signaling pathway." (PMID 39461979, 2024). "STAT3 is believed to be involved in the regulation of the tumor microenvironment." (PMID 39132168, 2024). "IL-10 and IL-21, but not IL-6, activate STAT3, promote tumor-specific Texterm cell-associated gene expression, and suppress TexProg cell-related gene expression, resulting in the development and enhanced effector functions of Texint cells in tumors." (PMID 38582965, 2024). "Additionally, we examined the molecular mechanisms of metastasis and examined therapeutic strategies to overcome tumor growth and metastasis in SMARCB1-deficient BLCA driven by STAT3 pathway upregulation." (PMID 38355560, 2024). "Since STAT3 has been shown to regulate PD-L1 expression in tumor cells, it is important to investigate whether this molecule also regulates macrophage PD-L1 expression in ALI/ARDS." (PMID 38440722, 2024). "In HCC cells, the STAT3 pathway plays a similar role, but its activation may be more complex due to the tumor microenvironment." (PMID 39409068, 2024). "The IL-1β/NFκB and IL-6/STAT3 signaling networks have well-established tumor-promoting functions." (PMID 39260693, 2024). "In terms of invasion, at adequate concentrations, lactic acid binds to GPR81 and enhances its expression via extracellular signaling and transcriptional activation through the 3stail3/STAT3 pathways, promoting tumor angiogenesis (VEGF) and immune evasion (PD-1)." (PMID 38625978, 2024).